PDP1 (pyruvate dehydrogenase phosphatase catalytic subunit 1)
Diseases named in the same sentence as PDP1 in open-access papers (continued):
Sharing a sentence is not in itself a finding about the gene and the disease.
cancer (157 papers, 2008 to 2026). A tumor composed of atypical neoplastic, often pleomorphic cells that invade other tissues. "Therefore, the underlying interaction between PDP1 and these immune cells might be partly responsible for the cancer-promoting effect of PDP1 in OC." (PMID 36276992, 2022). "PDP1 expression correlates with survival outcomes across various cancers, and tumors with low PDP1 levels tend to have relatively better survival outcomes." (PMID 40746885, 2025). "This would be in line with a recent study reporting that PDP1-mediated activation of PDH is required for histone acetylation under hypoxic conditions in cancer cell lines." (PMID 41230500, 2025). "In summary, PDP1 plays an important role in cancer metabolism by controlling the shift between oxidative phosphorylation and glycolysis, a key characteristic of cancer progression." (PMID 40491447, 2025). "This article reviews the effective integration of tumor metabolic reprogramming with clinical issues by PDP1, highlighting its potential implications for future cancer treatments." (PMID 40746885, 2025). "Analysis of PDP1 expression in pan-cancer found that PDP1 is widely expressed in epidermal growth factor-activated cells and various human malignant tumor cells." (PMID 40746885, 2025). "PDP1 is widely expressed in epidermal growth factor activated cells and various malignant human cancer cells." (PMID 38198170, 2024). "Basal PDP1 expression was studied in several human cancers showing entity-specific up or down regulation." (PMID 37935978, 2023). "Previously, it was reported that PDP1 expression and function are repressed in certain types of cancers, including AML." (PMID 37935978, 2023). "Pan-cancer analysis based on TCGA and GTEx data showed that PDP1 has an aberrant expression analysis in most cancers, including OC." (PMID 36276992, 2022). "Overall, our study demonstrated the [Ca2+]m-PDP1-PDH-histone acetylation axis activated by complex I defects contribute to intrinsic radioresistance in cancer cell." (PMID 34489398, 2021). "Here, we propose that the [Ca2+]m-PDP1-PDH-histone acetylation retrograde signaling activated by mitochondrial complex I defects contribute to cancer cell radioresistance, which provides new insight in the understanding of the mito-RTG." (PMID 34489398, 2021). "PDP1 accelerated intracellular ATP production, leading to sufficient energy to support rapid cancer progression." (PMID 32782783, 2020). "Human Pdp1 activity is inhibited by phosphorylation at a site distant from the active site (Y94), and phosphorylation at Y94 is commonly observed in human cancer cells and contributes to the Warburg effect." (PMID 28527238, 2017). "Interestingly, patients in the high PDP1 group consistently exhibited higher lactate scores compared to the middle and low PDP1 groups across multiple cancer types." (PMID 38198170, 2024). "Pyruvate dehydrogenase phosphatase 1 (PDP1) could accelerate intracellular ATP production and promote cancer progression through mTOR activation." (PMID 38506093, 2024). "However, little is known about the regulation of PDP1 by specific oncogenes and its effects on cancer biology." (PMID 37935978, 2023). "Our result showed that the cancer-promoting effect of PDP1 in OC might be dependent on these oncogenetic pathways." (PMID 36276992, 2022). "Another study also suggested that activation of PDP1 in cancer cells could induce a switch from cellular glycolysis to oxidative phosphorylation, the more efficient method of ATP production." (PMID 32782783, 2020). "AMPK was downregulated by PDP1 overexpression, resulting in mTOR activation and cancer progression." (PMID 32782783, 2020). "These divergent observations indicated that PDP1 may have different functions in particular types of cancers." (PMID 32782783, 2020). "The study shows that PDP1 enhances BRAF and MEK1 interaction and activates MAPK signaling, thereby promoting cancer progression." (PMID 40491447, 2025).
cancer (continued). "The study showed that increased PDP1 expression results in sustained suppression of AMPK signaling, subsequently facilitating mTOR and stimulating cancer cell proliferation, movement, and expansion." (PMID 40491447, 2025). "ACAT1 predominantly signals through inhibition of PDC by PDP1 and PDHA acetylation to enhance glycolysis and tumor growth, indicating the ACAT1-PDP1-PDHA axis a promising anti-cancer target." (PMID 38720812, 2024). "Moreover, PDP1 could significantly promote cancer cell proliferation, invasion, and migration." (PMID 36276992, 2022). "Similarly, hsa.miR.135b.5p displayed a positive regulation of PDP1 in LGG but a negative regulation in HNSC and PAAD, while showing a positive regulation in seven other cancer types." (PMID 38198170, 2024). "When the expression level of PDP1/PDH is too low under hypoxia, subsequent inhibition of HIF1A transcriptional activity and a reduction in its target gene, pyruvate dehydrogenase kinase 1 (PDK1), partially restore the activity of PDH for cancer cell proliferation." (PMID 39776803, 2025).
tumor (123 papers, 2008 to 2026). "Research on tumor cells demonstrated that the phosphorylation-deficient PDP1 Y94F mutant increased OXPHOS in mice, reduced cell proliferation under hypoxic conditions, and consequently slowed tumor growth." (PMID 40746885, 2025). "Phosphorylation at the Y381 site of PDP1 changes ACAT1 and PDP1 expression, regulates PDP1’s lysine acetylation, and impacts tumor cell metabolism and proliferation." (PMID 40746885, 2025). "While most of the mice in the PDK1 and PDP1 groups either died or had easily detectable tumors by day 16, mice in the EV group controlled the tumor better." (PMID 40857407, 2025). "Our findings further validate the significant role of PDP1 in the Warburg effect and tumor growth, highlighting its potential as an independent prognostic biomarker." (PMID 38198170, 2024). "The result indicated that PDP1 also had a higher protein level in OC tumor tissue compared with the normal tissue." (PMID 36276992, 2022). "PDP1 regulated the production of intracellular ATP, and supplementation with ATP recovered tumor cell proliferation and migration in PDP1 knockdown PDAC cells." (PMID 32782783, 2020). "The reconstitution of cellular ATP by acetate supplementation significantly reversed tumor cell proliferation in the cells with PDP1 knockdown." (PMID 32782783, 2020). "Constitutive activation of mTOR restored the proliferation rate in the PDAC cells with PDP1 knockdown, suggesting that mTOR activation is essential for PDP1-driven tumor cell growth in PDAC." (PMID 32782783, 2020). "Ectopic expression or knockdown of PDP1 was performed, and in vitro proliferation and migration, as well as in vivo tumor growth of PDAC, were measured." (PMID 32782783, 2020). "End-point measurement of the dissected tumors showed that tumor growth was accelerated by PDP1 overexpression." (PMID 32782783, 2020). "Another study, however, observed that phosphorylation of PDP1 at Tyr94 suppressed its activity and reduced tumor growth." (PMID 32782783, 2020). "The shPDHK1 and PDP1 overexpressing tumours displayed the greatest reduction in phospho serine 232 in vivo, and had the poorest growth as tumours." (PMID 27498883, 2016). "As an example, determining how PDP1 phosphorylation at Ty-94 leads to metabolic reprogramming in tumor cells may provide a deeper understanding of the role of PDP1 in tumor metabolism and drug resistance." (PMID 40491447, 2025). "Interestingly, they observed that phosphorylation of PDP1 at Tyr-94 is common in various human tumor cells, e.g., A549 lung cancer cells and MDA-MB-231 breast cancer cells." (PMID 40491447, 2025). "mTOR activation was responsible for the PDP1-induced tumor cell proliferation and invasion in PDAC." (PMID 32782783, 2020). "Under an in vivo imager, we observed that overexpression of PDP1 could significantly increase the signal intensity of tumor cell-derived luciferase, indicating a larger tumor formed by PDP1-overexpressing PDAC cells than the control cells." (PMID 32782783, 2020). "We used acetate as an alternative carbon source in tumor cells with PDP1 knockdown." (PMID 32782783, 2020). "To identify whether mTOR activity is crucial for PDP1-mediated tumor cell proliferation, we transfected a plasmid encoding the protein with a mutation that leads to constitutive activation of mTOR in PDAC cells with PDP1 knockdown." (PMID 32782783, 2020). "We found that in both cell lines, PDP1 overexpression significantly promoted the growth rate of the cells, while PDP1 knockdown had the opposite effects, suggesting that PDP1 expression may promote tumor cell proliferation in PDAC." (PMID 32782783, 2020). "Thus, PDP1 may affect the sensitivity of tumor cells to iron deposition by changing cell metabolism." (PMID 40337509, 2025). "Therefore, we explored the effect of PDP1 on the tumor immune microenvironment." (PMID 36276992, 2022).
tumor (continued). "PDP1 promoted the proliferation, colony formation, and invasion of PDAC cells in vitro and facilitated orthotopic tumor growth in vivo." (PMID 32782783, 2020). "Histological analysis by H&E staining showed that the PDP1-overexpressing PDAC cells had a more aggressive phenotype, e.g., an unclear border between pancreatic tissues and the tumor tissues, than the control cells." (PMID 32782783, 2020). "PDP1 overexpression downregulates adenosine monophosphate (AMP)-dependent protein kinase, resulting in the mechanistic target of rapamycin kinase (mTOR) activation and promoting tumor progression." (PMID 40746885, 2025). "Overexpression of PDP1 in PDAC cells promoted cell proliferation and migration in vitro and stimulated tumor growth in a murine model of PDAC, which could be related to the increase in intracellular energy production." (PMID 32782783, 2020). "For noninvasive monitoring of tumor growth, Panc2 cells with or without PDP1 overexpression were stably infected with a luciferase reporter, and luciferin could be catalyzed to emit bioluminescent signals." (PMID 32782783, 2020).
infection (37 papers, 2010 to 2026). The state of being infected such as from the introduction of a foreign agent such as serum, vaccine, antigenic substance or organism. "It is also apparent from our results that in addition to the expression of the PFKFB3 gene, infection of hSMs with the UT127 strain also induced higher levels of HIF1A, HK1, HK2, PDP1, and PDP2 genes compared with the infection with UT205." (PMID 35163725, 2022).
metabolic disorders (8 papers, 2014 to 2025). "While both PDP1 and PDP2 are involved in PDH activation, PDP1 more substantially impacts PDH activity and thus has been more directly linked to metabolic diseases." (PMID 40491447, 2025). "In this review, we discuss recent studies revealing the crucial role of PDP1 and its dysregulation in various metabolic disorders, thereby highlighting its potential as a therapeutic target for these debilitating diseases." (PMID 40491447, 2025). "While alterations in PDP1 expression or activity typically result in muscle and neurological pathologies, the dysregulation of PDP2 is more associated with liver-specific metabolic disorders, such as non-alcoholic fatty liver disease and insulin resistance." (PMID 40491447, 2025).
cardiovascular disease (3 papers, 2020 to 2024). "pdp1 abnormal expression was associated with cardiomyocytes differentiation and cardiovascular disease." (PMID 35544480, 2022).
PDP1 also shares sentences with these, for which no sentence is quoted: Sepsis (21 papers); diabetes (19); melanoma (16); Obesity (14); Insulin resistance (13); heart failure (11); Hyperglycemia (11); ischemia (8); type 2 diabetes (6); cardiac arrest (5); epilepsy (5); hepatoma (5); Leigh syndrome (5); Thiamine deficiency (5); Alzheimer disease (4); brain injury (4); cardiac hypertrophy (4); fatty liver disease (4); mitochondrial disease (4); neuroblastoma (4); atherosclerosis (3); Cachexia (3); cardiomyopathy (3); Cerebral ischemia (3); colorectal tumor (3); diabetic cardiomyopathy (3); hypertriglyceridemia (3); liver cancer (3); pulmonary hypertension (3); amyotrophic lateral sclerosis (2).
A further 93 diseases each share a sentence with PDP1 in 2 papers or fewer.